PDE6C (phosphodiesterase 6C)
Description:
As cone-specific cGMP phosphodiesterase, it plays an essential role in light detection and cone phototransduction by rapidly decreasing intracellular levels of cGMP.
Synonyms: PDEA2; ACHM5; COD4
Tractability: Small molecule: an approved drug acts on it; a structure with a bound ligand is known; a high-quality ligand is known; it belongs to a druggable protein family. Antibody: UniProt places it where antibodies can reach, with high confidence; its Gene Ontology location is reachable by antibodies, with medium confidence. PROTAC: a small molecule that binds it is known.
Target class: Enzyme; Phosphodiesterase; Phosphodiesterase 6; Phosphodiesterase 6C
Gene: Protein-coding gene on chromosome 10 (93,612,537 to 93,666,010, forward strand). Ensembl gene ENSG00000095464.
Subcellular location: Cell membrane
Gene Ontology:
Molecular function: 3',5'-cyclic-GMP phosphodiesterase activity; 3',5'-cyclic-AMP phosphodiesterase activity; 3',5'-cyclic-nucleotide phosphodiesterase activity; phosphoric diester hydrolase activity
Biological process: nuclear-transcribed mRNA catabolic process, no-go decay; transducin-mediated opsin signaling pathway; visual perception; negative regulation of cAMP/PKA signal transduction; phototransduction, visible light; signal transduction
Cellular component: cone photoreceptor disc membrane; photoreceptor disc membrane; plasma membrane
Genetic constraint (gnomAD): Loss-of-function variants: 52 observed, 67.14 expected, observed/expected ratio (o/e) 0.77, 90% interval 0.62 to 0.98. The upper end of that interval is the gene's LOEUF score, 0.98, which puts it in group 4 of 6, group 1 being the genes least tolerant of losing a copy. Missense variants: 623 observed, 721.48 expected, observed/expected ratio (o/e) 0.86, 90% interval 0.81 to 0.92. Synonymous variants: 258 observed, 268.89 expected, observed/expected ratio (o/e) 0.96, 90% interval 0.87 to 1.06.
Homologues: Orthologues: chimpanzee PDE6C (99% identical), macaque PDE6C (99% identical), pig PDE6C (90% identical), guinea pig PDE6C (90% identical), rabbit PDE6C (90% identical), dog PDE6C (87% identical), mouse Pde6c (87% identical), rat Pde6c (87% identical), tropical clawed frog pde6c (77% identical), zebrafish pde6c (69% identical), Drosophila melanogaster Pde11 (30% identical), Drosophila melanogaster Pde8 (14% identical), and 2 more. Paralogues in human: PDE6B (64% identical), PDE6A (63% identical), PDE11A (31% identical), PDE5A (28% identical), PDE2A (23% identical), PDE10A (22% identical), PDE3A (17% identical), PDE4A (17% identical), PDE4B (17% identical), PDE4D (17% identical), PDE1C (16% identical), PDE3B (16% identical), and 8 more.
Diseases named in the same sentence as PDE6C in open-access papers:
PDE6C is named in the same sentence as 30 diseases in open-access papers, as found by Europe PMC text mining. Sharing a sentence is not in itself a finding about the gene and the disease. The quoted sentences say what the papers report.
achromatopsia (27 papers, 2013 to 2025). Achromatopsia (ACHM) is a rare autosomal recessive retinal disorder characterized by color blindness, nystagmus, photophobia, and severely reduced visual acuity due to the absence or impairment of cone function. "While PDE6C accounts for a minority of cases of achromatopsia in Europe (< 2%), variants in this gene are a leading cause of achromatopsia in Japan and Korea." (PMID 40013354, 2025). "While this study demonstrated an association between PDE6C and high myopia, achromatopsia (as a clinical diagnosis) is classically associated with hyperopia." (PMID 41153400, 2025). "Refractive errors in patients with achromatopsia appear to be gene-specific, where biallelic pathogenic variants in PDE6C and PDE6H tend to be associated with myopia." (PMID 41153400, 2025). "WES results showed two variants, a novel null variant (p.Trp548Ter) in the PDE6C gene causing COD type 4 (Achromatopsia) and a previously reported variant (p.Ile84Thr) in the PDZD7 gene causing NSHL." (PMID 38956522, 2024). "A number of studies have shown that the mutation in PDE6C will affect both cone and rod photoreceptors and eventually cause retinal degenerative diseases, such as achromatopsia in humans and retinal degeneration in zebrafish." (PMID 39372898, 2024). "In this study, we aimed to correct a homozygous PDE6C pathogenic variant in hiPSCs derived from a patient affected by achromatopsia through CRISPR/Cas9 and TALENs technologies." (PMID 36835061, 2023). "Korean patients with achromatopsia showed similar clinical features but a higher prevalence of PDE6C variants than those of other ethnic groups." (PMID 36833446, 2023). "In this model, while the disease-causing mutation was identified, PDE6C mutations only account for 1% of clinical cases of achromatopsia in humans, with CNGB3 and CNGA3 accounting for the majority of cases." (PMID 35205388, 2022). "Our data extended the phenotypic spectrum of retinal disorders caused by PDE6C variants and provided new clinical and genetic information on achromatopsia." (PMID 32306724, 2020). "The patients identified with achromatopsia segregated a homozygous missense variant (c.C1775A:p.A592D) in PDE6C gene located on chromosome 10q23." (PMID 32306724, 2020). "In this study, we identified a novel PDE6C variant in two cases of achromatopsia with macular atrophy." (PMID 32306724, 2020). "Variants in PDE6C are an uncommon cause of achromatopsia, comprising less than 2% of the cases, and their associated phenotypes have poorly been described in the literature." (PMID 32306724, 2020). "The clinical phenotyping of patients with achromatopsia harboring variants in PDE6C has poorly been described in the literature." (PMID 32306724, 2020). "The present study reports the comprehensive clinical specifications of two siblings with achromatopsia while harboring the homozygous likely pathogenic variant in PDE6C." (PMID 32306724, 2020). "We present a spontaneously occurring NHP model of achromatopsia presenting very early in life (1 year, 10 months) caused by R565Q mutation of the PDE6C gene, altering the catalytic domain of the PDE6C enzyme and nullifying its enzymatic hydrolysis of cGMP." (PMID 30667376, 2019). "Mutations in PDE6C are responsible for approximately 1% of achromatopsia cases in humans and 1% of cone dystrophy patients." (PMID 30667376, 2019). "In human subjects with PDE6C-associated achromatopsia, the fundus appears largely normal with subtle foveal pigmentary changes." (PMID 30667376, 2019). "Genetic sequencing confirmed a homozygous R565Q missense mutation in the catalytic domain of PDE6C, a cone-specific phototransduction enzyme associated with achromatopsia in humans." (PMID 30667376, 2019). "In patients with PDE6C-associated achromatopsia, mutations can lead to protein degradation, cellular mislocalization, or enzymatic dysfunction." (PMID 30667376, 2019).
achromatopsia (continued). "These animals are homozygous for a missense mutation altering the catalytic domain of their PDE6C proteins, a gene associated with achromatopsia or cone dystrophy in humans." (PMID 30667376, 2019). "We identified a novel variant in the PDE6C gene, related to achromatopsia." (PMID 38956522, 2024). "Potential pathogenic variants in the cone-specific PDE6C gene are associated with achromatopsia." (PMID 32306724, 2020). "A naturally occurring, non-human primate (NHP) model of achromatopsia with a homozygous mutation in the PDE6C gene had phenotypic similarities to that of the human achromatopsia patients and was used to understand the cone-mediated visual loss associated with CNGA3/B3 mutations." (PMID 32967234, 2020). "Finally, an achromatopsia model with PDE6C mutation was also identified recently." (PMID 35205388, 2022). "Therefore, loss of function of PDE6C will give rise to achromatopsia." (PMID 32306724, 2020). "Currently, six genes that cause achromatopsia have been discovered, including CNGA3, CNGB3, GNAT2, PDE6C, PDE6H and ATF6." (PMID 38298913, 2024). "We identified variants believed to be disease causing in five of the known achromatopsia genes: CNGA3; CNGB3; GNAT2; PDE6C and PDE6H; and novel variants were identified in CNGB3 and PDE6C." (PMID 36980963, 2023). "In PDE6C-achromatopsia patients, the same proportion was significantly lower than that of patients with other causative genes (0% vs. 58.3%; p = 0.003)." (PMID 36833446, 2023). "The cone-specific α’-subunits are encoded by the PDE6C gene, Mutations in the rod-specific PDE6A gene cause RP while mutations in PDE6C result in cone dystrophy and achromatopsia." (PMID 35693295, 2022). "Pathogenic variants in six genes (CNGA3, CNGB3, GNAT2, ATF6, PDE6C, and PDE6H) have been identified in humans with achromatopsia (OMIM 216900)." (PMID 34830323, 2021). "Naturally occurring achromatopsia based on mutations in other genes have been described in Awassi sheep (CNGA3) and in mice (CNGA3, GNAT2 and PDE6C)." (PMID 23601474, 2013). "Achromatopsia is caused by sequence variants in CNGA3, CNGB3, GNAT2, PDE6H, PDE6C, and ATF6." (PMID 39273686, 2024). "However, reanalysis helped to identify, in each parent, two heterozygous mutations in MYL3 and PDE6C, responsible for two different conditions: heart defect (OMIM #608751) and achromatopsia (OMIM #613093), respectively." (PMID 30665423, 2019). "The low proportion of patients with FAF Groups 3 and 4, and OCT Grades 3 and 4 in our study, can support the speculation that those stages are short transitional state of the disease natural history, in contrast to CNGB3-, CNGA3-, and PDE6C-achromatopsia where Grade 4 is more common." (PMID 33737031, 2021). "The similar clinical presentation between familial achromatopsia in humans and bovine recessive day-blindness led to the hypothesis that a protein-changing variant within CNGA3, CNGB3, GNAT2, ATF6, PDE6C, and PDE6H would be associated with achromatopsia of Original Braunvieh calves." (PMID 34830323, 2021). "Mutations in CNGA3 (MIM#600053), CNGB3 (MIM#605080), GNAT2 (MIM#139340), and PDE6C (MIM#600827) have been detected in four probands with OT, which all encode cone phototransduction pathway proteins, suggesting a pathomechanistic overlap with achromatopsia (ACHM)." (PMID 28829391, 2017). "Pathogenic variants in different genes such as CNGA3, CNGB3, GNAT2, PDE6H, ATF6 and PDE6C have been reported to be relevant to COD, cone-rod dystrophy (CORD) and achromatopsia (ACHM) diseases." (PMID 38956522, 2024). "If L and M cones in human achromatopsia patients do not express cone and rod Pγ, they would fail to signal, but they can escape cell death due to residual PDE6C activity." (PMID 38110033, 2024).
retinal degeneration (6 papers, 2014 to 2024). Degeneration of the retina. "Group (b) was very small with only 9 genes, and it did not make a cluster of functionally related GO terms, although 6 of 9 genes were annotated as causal genes for retinal degeneration (Abca4, Elovl2, Fscn2, Nxnl1, Pde6c, and Pde6h)." (PMID 24747725, 2014). "In this study, we evaluated SchB on retinal degeneration induced by pde6c mutation in zebrafish." (PMID 26930483, 2016). "It has also been indicated that obliteration of Pγ in mouse photoreceptors significantly reduces PDE6C hydrolyses and leads to retinal degeneration, despite the expectation that the removal of the inhibitory Pγ subunit from holoPDE6C would activate the enzyme." (PMID 32306724, 2020).
cone dystrophy (5 papers, 2017 to 2023). An inherited ocular disorder characterized by the loss of cone cells, the photoreceptors responsible for both central and color vision. "Here we report for the first time the association of APS1 with PDE6C-related cone dystrophy, in a large inbred Saudi family." (PMID 37433860, 2023). "Although, cone dystrophy associated PDE6C variant independently segregated from RP associated TULP1 variant in family 3, however, nystagmus and complete blindness at the age of 20 years were observed in family members who carried both PDE6C and TULP1 variants." (PMID 37165311, 2023). "In current study, the identified frameshift deletion (p.Asn161ThrfsTer33) in the PDE6C has been predicted as a loss of function variant due to the degradation of expressed aberrant transcript by NMD that can cause progressive cone dystrophy." (PMID 37165311, 2023). "However, mild features of RP were observed in some individuals of the same family who were detected homozygous for only TULP1 variant alleles and cone dystrophy was observed in an individual who was carrying only PDE6C variant alleles in homozygous state." (PMID 37165311, 2023). "In summary we present for the first time the co-occurrence of PDE6C-related cone dystrophy with APS1." (PMID 37433860, 2023). "We report the co-inheritance for APS1 and PDE6C-related cone dystrophy, an unusual example of two seemingly independent recessive conditions coinciding within a family." (PMID 37433860, 2023).
myopia (5 papers, 2020 to 2025). "Similarly, a recent study reported high myopia (> 6 diopters) in five (62.5%), mild hyperopia in two (25%), and myopic astigmatism in one (12.5%) of eight patients with PDE6C-Associated Achromatopsia14." (PMID 33168939, 2020). "It is interesting that our patients with PDE6C-associated ACHM showed a longer average AL, suggestive of higher myopia." (PMID 35704304, 2022). "Why some forms of cone dysfunction predispose to myopia (including PDE6C‐associated disease), whilst others do not, is of interest." (PMID 40013354, 2025).
breast carcinoma (2 papers, 2013 to 2025). "PDE6C was highly and significantly expressed in all four of these breast cancer cell lines." (PMID 24683528, 2013). "In this paper we show significant expression of PDE6B, PDE6C, and PDE6D, in human breast cancer cell lines and patients’ breast cancer tissues." (PMID 24683528, 2013).
Nystagmus (2 papers, 2023 to 2024). Rhythmic, involuntary oscillations of one or both eyes related to abnormality in fixation, conjugate gaze, or vestibular mechanisms. "However, in addition to decreased VA and nystagmus, complete ACHM, macular atrophy and COD/CORD are also evident in our patients due to the novel pathogenic variant in the PDE6C gene." (PMID 38956522, 2024).
retinal dystrophies (2 papers, 2023). "This explains why pathogenic variants in PDE6A (OMIM #180071), PDE6B (OMIM #180072) and PDE6G (OMIM #180073) cause predominantly rod-involving retinal dystrophies, whereas pathogenic variants in PDE6C and PDE6H (OMIM #600827 and #601190) lead to retinal dystrophies which predominantly affect cones." (PMID 37433860, 2023). "In addition, the reported variants were of clinical significance as the PDE6C variant was detected novel, whereas TULP1, MERTK, and MYO7A variants were detected rare and first time found segregating with retinal dystrophies in Pakistani consanguineous families." (PMID 37165311, 2023).
autosomal dominant cerebellar ataxia (1 paper, 2017). A clinically and genetically heterogeneous group of neurodegenerative diseases characterized by a slowly progressive ataxia of gait, stance and limbs, dysarthria and/or oculomotor disorder, due to cerebellar degeneration in the absence of coexisting diseases. "Considering the inner linkage between autosomal-dominant cerebellar ataxia and epilepsy in human beings, our predicted gene PDE6C may also contribute to the progression of epilepsy, validating our prediction." (PMID 28255556, 2017).
Rb (1 paper, 2013). "We previously reported that cone photoreceptor-specific phototransduction enzyme PDE6C was highly expressed in primary Rb tumor yet was significantly reduced in tumor-derived adherent cultures." (PMID 23826078, 2013).
tumor (4 papers, 2013 to 2020). "In contrast, PDE6B and PDE6C were significantly, and in many cases highly, expressed in all eight patients’ tumor tissues." (PMID 24683528, 2013). "We then examined the expression of retinal-associated genes within a set of differentially expressed genes following MYCNOS1 silencing and found that expression of cone genes, including ARR3, GNAT, and PDE6C, was downregulated in MYCNOS1-depleted tumor cells." (PMID 33270844, 2020). "In contrast, the expression levels of cone-enriched genes (PDE6C and ARR3) were high in tumor and further enriched in organoids, compared with fetal retina." (PMID 30353124, 2018).
infection (2 papers, 2015 to 2024). The state of being infected such as from the introduction of a foreign agent such as serum, vaccine, antigenic substance or organism. "In addition to immunity, genes associated with metabolism (e.g. SLC5A6, SLC2A5, UGT2A3, and PDE6C) as well as membrane proteins, like TM4SF4, were also detected with a significantly higher expression level in CE infection sheep at four hour post infection, when compared with healthy controls." (PMID 26252489, 2015).
retinal disorder (1 paper, 2020). Any disease or disorder of the retina. "Our data extended the phenotypic spectrum of retinal disorders caused by PDE6C variants and provided new clinical and genetic information." (PMID 32306724, 2020).
PDE6C also shares sentences with these, for which no sentence is quoted: cone-rod dystrophy (4 papers); cone and cone-rod dystrophies (3); Blindness (2); macular degeneration (2); Photophobia (2); retinitis pigmentosa (2); Astigmatism (1); cataract (1); epilepsy (1); Hyperglycemia (1); hyperopia (1); intrahepatic cholangiocarcinoma (1); mood disorder (1); night blindness (1); osteoporosis (1); Progressive cone dystrophy (1); retinoschisis (1); Visual impairment (1).